EOMES (eomesodermin)
Description:
Functions as a transcriptional activator playing a crucial role during development. Functions in trophoblast differentiation and later in gastrulation, regulating both mesoderm delamination and endoderm specification. Plays a role in brain development being required for the specification and the proliferation of the intermediate progenitor cells and their progeny in the cerebral cortex. Required for differentiation and migration of unipolar dendritic brush cells. Also involved in the differentiation of CD8+ T-cells during immune response regulating the expression of lytic effector genes.
Synonyms: TBR2
Tractability: PROTAC: ubiquitination databases record sites on it.
Gene: Protein-coding gene on chromosome 3 (27,715,949 to 27,722,711, reverse strand). Ensembl gene ENSG00000163508.
Subcellular location: Nucleus
Subcellular location (Human Protein Atlas): Nucleoplasm; Cytosol; Golgi apparatus
Pathways (Reactome):
Developmental Biology: Cardiogenesis; Epithelial-Mesenchymal Transition (EMT) during gastrulation; Formation of definitive endoderm; Germ layer formation at gastrulation; POU5F1 (OCT4), SOX2, NANOG repress genes related to differentiation
Reproduction: Specification of primordial germ cells
Gene Ontology:
Molecular function: sequence-specific DNA binding; sequence-specific double-stranded DNA binding; DNA binding; DNA-binding transcription factor activity, RNA polymerase II-specific; RNA polymerase II cis-regulatory region sequence-specific DNA binding; RNA polymerase II-specific DNA-binding transcription factor binding; transcription corepressor activity; chromatin binding; chromatin DNA binding; DNA-binding transcription factor activity; RNA polymerase II transcription regulatory region sequence-specific DNA binding
Biological process: brain development; CD8-positive, alpha-beta T cell differentiation involved in immune response; positive regulation of transcription by RNA polymerase II; cell differentiation involved in embryonic placenta development; endoderm formation; endodermal cell fate specification; mesoderm formation; mesodermal to mesenchymal transition involved in gastrulation; negative regulation of transcription by RNA polymerase II; positive regulation of DNA-templated transcription; regulation of transcription by RNA polymerase II; astrocyte differentiation; cerebral cortex development; cerebral cortex neuron differentiation; chromatin remodeling; gene expression; neuron migration; regulation of DNA-templated transcription
Cellular component: chromatin; nucleoplasm; nucleus
Genetic constraint (gnomAD): Loss-of-function variants: 17 observed, 51.74 expected, observed/expected ratio (o/e) 0.33, 90% interval 0.22 to 0.49. The upper end of that interval is the gene's LOEUF score, 0.49, which puts it in group 2 of 6, group 1 being the genes least tolerant of losing a copy. Missense variants: 839 observed, 827.15 expected, observed/expected ratio (o/e) 1.01, 90% interval 0.96 to 1.07. Synonymous variants: 407 observed, 345.18 expected, observed/expected ratio (o/e) 1.18, 90% interval 1.09 to 1.28.
Homologues: Orthologues: chimpanzee EOMES (99% identical), macaque EOMES (99% identical), dog EOMES (97% identical), guinea pig EOMES (95% identical), pig EOMES (94% identical), mouse Eomes (91% identical), rat Eomes (90% identical), tropical clawed frog eomes (66% identical), zebrafish eomesa (60% identical), rabbit EOMES (57% identical), zebrafish eomesb (45% identical), Drosophila melanogaster ocm (17% identical), and 10 more. Paralogues in human: TBR1 (46% identical), TBX21 (33% identical), TBX2 (19% identical), MGA (19% identical), TBX5 (19% identical), TBX3 (18% identical), TBX15 (18% identical), TBX4 (18% identical), TBXT (17% identical), TBX1 (17% identical), TBX18 (17% identical), TBX22 (16% identical), and 4 more.
Diseases named in the same sentence as EOMES in open-access papers:
EOMES is named in the same sentence as 57 diseases in open-access papers, as found by Europe PMC text mining. Sharing a sentence is not in itself a finding about the gene and the disease. The quoted sentences say what the papers report.
microcephaly (17 papers, 2012 to 2024). A congenital or acquired developmental disorder in which the circumference of the head is smaller than normal for the person's age and sex. "PMG, microcephaly and agenesis of the corpus callosum are described in inactivation of the T-box transcription factor gene EOMES." (PMID 25047116, 2014). "Indeed, Tbr2+ IPs are increasingly recognized as important regulators of human brain development, as congenital EOMES enhancer mutations cause microcephaly." (PMID 32238264, 2020). "The spatial patterning of the cortex is under genetic control and one transcription factor responsible for the cortical area map, EOMES (eomesodermin), has been shown to be defective in a syndrome which includes PMG, microcephaly and agenesis of the corpus callosum." (PMID 25047116, 2014).
melanoma (8 papers, 2013 to 2023). A malignant, usually aggressive tumor composed of atypical, neoplastic melanocytes. "Treg signature genes CXCR5, TNFRSF9, CCR7, STAT1, GBP4, and EOMES were significantly upregulated in the young cohort and were correlated with higher survival in melanoma, while ID3, IL-17A, IL-17F, RDH10 and IL-11 were significantly upregulated in the old cohort." (PMID 36135194, 2022). "Further supporting a role of obesity-induced T cell exhaustion in melanoma is the increase in gene expression of inhibitory molecules PD-1, TIGIT, EOMES, TIM3 and LAG3 found in melanoma patients with a high body mass index (BMI)." (PMID 32549336, 2020). "The overall survival rate of patients with high expressions of CCR7, CXCR5, EOMES, GBP4, TNFRSF9 and STAT1 in melanoma was significantly higher, which is consistent with the significantly higher survival rate observed for the young cohort receiving immunotherapy." (PMID 36135194, 2022).
COVID-19 (7 papers, 2021 to 2025). A disease caused by infection with severe acute respiratory syndrome coronavirus 2. "Specifically, the T-box transcription factors T-bet (P=0.051) and Eomesodermin were higher in PB from MIS-C compared to pediatric COVID-19." (PMID 33653907, 2021). "Notably, the specific inclusion of cytotoxic-T-cell-specific genes (EOMES and SGK1) in the 20 gene signature differentiating critical patients further supports a role for inability to clear viral infection in COVID-19 severity." (PMID 36902333, 2023). "The upregulation in EOMES, a transcription factor involved in the T-cell exhaustion process in severe COVID-19 patients, in the comparison describing infected and not vaccinated cases, suggests that EOMES may play a role in the development of T-cell exhaustion." (PMID 38474155, 2024).
bladder cancer (6 papers, 2012 to 2023). "The EOMES gene has been associated with multiple sclerosis and bladder cancer." (PMID 24481203, 2013). "The methylation status of a 4-gene panel (HOXA9, EOMES, POU4F2, and ZNF154) was significantly different between urine samples from bladder cancer patients and healthy individuals." (PMID 37627900, 2023). "In another study, the correlation between the methylation levels of EOMES, HOXA9, POU4F2, TWIST1, VIM, and ZNF154 in urine specimens and bladder cancer recurrence surveillance was discovered by real-time PCR." (PMID 33388091, 2021). "To analyze samples negative for BCL2 methylation, we expanded the MethyLight-based analysis by six additional promoter CpG islands previously reported to be frequently hypermethylated in bladder cancer, including CCNA1, EOMES, HOXA9, POU4F2, SALL3 and VIM2." (PMID 24732047, 2014). "Reinert and collaborators established a detailed mapping of the methylome in bladder cancer and identified four novel DNA methylation marks: HOXA9, ZNF154, POU4F2, and EOMES." (PMID 22829811, 2012). "In addition, a 6-gene panel (HOXA9, EOMES, POU4F2, TWIST1, VIM, and ZNF154) was highly hypermethylated in the urine of bladder cancer patients as compared to healthy individuals." (PMID 37627900, 2023).
colorectal cancer (4 papers, 2008 to 2021). A primary or metastatic malignant neoplasm that affects the colon or rectum. "EOMES overexpression in colorectal cancers was found to be important in the reciprocal regulation of BIRC5 and pro-apoptotic Bcl-2 modifying factor." (PMID 34685742, 2021). "Previous studies also show that EOMES are overexpressed in colorectal cancer." (PMID 22053823, 2011).
hepatocellular carcinoma (4 papers, 2014 to 2025). A malignant tumor that arises from hepatocytes. "In addition, EOMES has also been confirmed to have potential anti-cancer functions through siRNA experiments, and was regarded as a candidate tumor suppressor gene for human hepatocellular carcinoma." (PMID 30233644, 2018). "Moreover, EOMES is also an established tumor suppressor in Hepatocellular Carcinoma." (PMID 29914366, 2018). "​In hepatocellular carcinoma, itaconate promotes CD8+ T cell exhaustion by enhancing H3K4me3 histone modifications at the promoter region of the transcription factor Eomesodermin (EOMES), leading to PD-1 and TIM-3 expression." (PMID 40931345, 2025).
lymphoma (4 papers, 2022 to 2025). A malignant (clonal) proliferation of B- lymphocytes or T- lymphocytes which involves the lymph nodes, bone marrow and/or extranodal sites. "Using exome sequencing, they identified six recurrent, rare, and potentially deleterious variants within 5 kb of lymphoma-associated GWAS loci in 75 MM cases (BTNL2, EOMES, TNFRSF13B, IRF8, ACOXL, TSPAN32)." (PMID 41300981, 2025). "The chronic stimulation by lymphoma results in T cell exhaustion driven by transcription factors such as TOX, EOMES, BATF, and IRF4, which is further affected by the immunosuppressive microenvironment and more lines of therapy." (PMID 40248244, 2025). "Interestingly, the upregulated transcriptome of these lymphomas also includes the transcriptional factor TBX21 (also known as T‐BET), the cotranscriptional regulator EOMES, and TBX21‐dependent gene signatures." (PMID 35895495, 2022).
breast carcinoma (3 papers, 2018 to 2022). "According to the result of TF analysis, although most of the TFs have been reported to be associated with breast cancer, there were still TFs such as EOMES, POU3F2, NR3C1, and RUNX1 that were less reported in breast cancer." (PMID 36313438, 2022). "In terms of defining T cell exhaustion, multiple reports have suggested the combination of PD-1 and transcription factor Eomesodermin (EOMES) might be more accurate, and this warrants further study in a breast cancer setting." (PMID 30728081, 2019).
lung carcinoma (3 papers, 2019 to 2022). "Other data have shown that metformin can benefit lung cancer patients via AMPK-mediated downregulation of miR-107 and upregulation of eomesodermin (Eomes)." (PMID 34502359, 2021).
multiple sclerosis (3 papers, 2013 to 2025). A progressive autoimmune disorder affecting the central nervous system resulting in demyelination. "Parnell GP and colleagues investigated the gene expression level of two distinct transcription factors encoded by TBX21 and EOMES genes in T- and NK cells in patients with multiple sclerosis (MS)." (PMID 37950255, 2023). "We performed a prospective longitudinal study over one year to investigate the role of Eomesodermin+ T cells in multiple sclerosis progression and neurodegeneration." (PMID 41346466, 2025). "In summary, Eomesodermin+ Th cells may shape a dysregulated and proinflammatory immune milieu, driving disease progression and neurodegeneration in secondary progressive multiple sclerosis with potential as both biomarker and therapeutic target." (PMID 41346466, 2025).
acute myeloid leukemia (2 papers, 2021 to 2022). Acute myeloid leukemia (AML) is a group of neoplasms arising from precursor cells committed to the myeloid cell-line differentiation. "In this context, reduced expression of lncRNA RP11-222K-16.2 in NK cells of acute myeloid leukemia (AML) patients eliminates NK cell differentiation via cis-acting regulation of a nearby gene that encodes for the eomesodermin protein, a transcriptional activator of genes related to NK development." (PMID 34943820, 2021). "A transcription factor Eomesodermin (Eomes) is expressed on CD8+ T cells of patients diagnosed with acute myeloid leukemia, and it can enhance the expression of TIGIT by binding to its promoter region." (PMID 35720417, 2022).
atherosclerosis (2 papers, 2021 to 2023). A disease characterized by the build-up of fatty material and calcium deposition in the arterial wall resulting in partial or complete occlusion of the arterial lumen. "Up-regulated DEGs of this gene signature included T-cell development, growth and proliferation genes (BATF, CCL5, CD2, EOMES) and F2R, a recognized genetic locus influencing clinical CVD and atherosclerosis development." (PMID 37205656, 2023). "CD4+ Th1 responses, directed by the Th1 master T-box transcriptional regulators T-BET and (to some extent) Eomesodermin (EOMES) are the most prevalent Th subset in atherosclerotic plaques and promote atherosclerosis progression and severity." (PMID 33483751, 2021).
experimental autoimmune encephalomyelitis (2 papers, 2020 to 2021). An autoimmune demyelinating disease of the central nervous system that is produced experimentally in animals by the injection of homogenized brain or spinal cord in Freund's adjuvant. "In addition, it has been shown that CD4+ T cells expressing the T-box transcription factor Eomesodermin (EOMES) have cytotoxic features and are essential for chronic neuroinflammation observed in experimental autoimmune encephalomyelitis (EAE)." (PMID 32190092, 2020).
HIV-1 infection (2 papers, 2021). The type species of lentivirus and the etiologic agent of acquired immunodeficiency syndrome (AIDS). "In chronic HIV-1 infection, CD8 T-cell exhaustion is linked to an intermediate transcriptional phenotype expressing high levels of Eomesodermin (Eomes) that is directly linked to co-expression of PD-1 and TIGIT." (PMID 34712231, 2021). "In addition, viral induced CD8 T cell exhaustion has been linked to a decrease in T-BET and an increase in the expression of the closely related T-box family transcription factor EOMES, a point also validated in human during HIV-1 infection." (PMID 33507150, 2021).
leukemia (2 papers, 2020 to 2021). A malignant (clonal) hematologic disorder, involving hematopoietic stem cells and characterized by the presence of primitive or atypical myeloid or lymphoid cells in the bone marrow and the blood. "We hypothesized that EOMES is involved in T-cell dysfunction in CLL, and the increased risk for CLL development in individuals with a SNP in the EOMES locus is due to a reduced ability of CD8+ T cells to control leukemia progression." (PMID 33731848, 2021). "In support of a role for CD4+ T-cells in leukemia control, we have recently shown that these cells are able to control CLL progression in the absence of CD8+ T-cells in the TCL1 AT mouse model in an Eomesodermin (Eomes)- and Il10rb-dependent manner." (PMID 32457353, 2020).
liver cancer (2 papers, 2021 to 2022). An epithelial or non-epithelial malignant neoplasm that arises from the liver. "Moreover, nine activated memory CD4 T cell-related genes were associated with liver cancer prognosis [e.g., eomesodermin (EOMES), glutathione S-transferase (CST7), and adhesion G protein-coupled receptor E2 (EMR2)]." (PMID 34980144, 2022). "In the present study, EOMES was a T cell-related gene associated with liver cancer prognosis." (PMID 34980144, 2022). "The survival analysis showed that the T cell-related genes EOMES, CST7, CD5L, and EMR2 were associated with the prognosis of liver cancer." (PMID 34980144, 2022). "Considering these results together, we speculate that EOMES may be the potential target of has-miR-23b-3p and has-miR-23a-3p in liver cancer and that they play important roles in the progression of the disease." (PMID 34980144, 2022). "In addition, there were 30 CD8 T cell-related genes associated with liver cancer prognosis [e.g., CD5 molecules like CD5L, EOMES, and CST7]." (PMID 34980144, 2022). "Upregulated expression of T cell-related genes including EOMES, CST7, and CD5L indicated the favorable prognosis of liver cancer." (PMID 34980144, 2022). "The survival analysis revealed that upregulated expression of T cell-related genes including EOMES, CST7, and CD5L indicated the favorable prognosis of liver cancer." (PMID 34980144, 2022).
lymphopenia (2 papers, 2014 to 2016). Reduction in the number of lymphocytes. "Recent data using anti-tumor models has demonstrated that strong stimulation via OX40 and OX40-L, 4-1BB activation or OX40 stimulation and lymphopenia could enhance CD4 CTL activity in a manner dependent on Eomesodermin." (PMID 24586481, 2014).
T cell lymphoma (2 papers, 2025 to 2026). "In response to a phorbol 12-myristate 13-acetate (PMA) and ionomycin (IM) stimulation, kujigamberol suppressed interferon-γ (IFN-γ) and interleukin-2 (IL-2) mRNA expression in murine T-cell lymphoma BW5147 cells stably transfected with the T-box transcription factor eomesodermin." (PMID 40430387, 2025).
acute respiratory distress syndrome (1 paper, 2021). Progressive and life-threatening pulmonary distress in the absence of an underlying pulmonary condition, usually following major trauma or surgery. "Furthermore, plasmablasts in MIS-C patients express higher levels of the transcription factors T-bet and Eomesodermin when compared to pediatric COVID-19 patients with and without acute respiratory distress syndrome (ARDS)." (PMID 35011627, 2021).
alopecia areata (1 paper, 2026). Loss of scalp and body hair involving microscopically inflammatory patchy areas. "Compared with healthy controls, mRNA levels of EOMES, GZMA, IL2RB, and IL2RG were significantly upregulated in alopecia areata (AA) lesional scalp (all p<0.01), whereas androgenetic alopecia (AGA) scalp showed no significant increase relative to controls (all p>0.05)." (PMID 41602548, 2026).
Brain atrophy (1 paper, 2025). Partial or complete wasting (loss) of brain tissue that was once present. "Conclusively, voxel-based morphometry analysis revealed pronounced infratentorial brain atrophy in a sub-cohort of patients with higher Eomesodermin+ Th frequencies." (PMID 41346466, 2025).
cardiomyopathy (1 paper, 2021). A disease of the heart muscle or myocardium proper. "In response to IL-27, gene expression of TBX21, EOMES, and CXCL9, which are activated downstream of STAT1, STAT3, and STAT5 phosphorylation, was lower in patients with cardiomyopathy (i.e., the G1 and G2 groups) than that in uninfected subjects." (PMID 34061845, 2021).
cholangiocarcinoma (1 paper, 2022). A carcinoma that arises from the intrahepatic biliary tree (intrahepatic cholangiocarcinoma) or from the junction, or adjacent to the junction, of the right and left hepatic ducts (hilar cholangiocarcinoma). "Therefore, PD-1 and EOMES represent two independent exhaustion pathways in all three types of cholangiocarcinoma; and other T cell exhaustion markers including LAG3, TIM3, TOX were thus investigated below." (PMID 35346322, 2022).
chronic lymphocytic leukemia (1 paper, 2021). "Genome-wide association studies (GWAS) have shown that a single-nucleotide polymorphism (SNP) affecting the transcription factor Eomesodermin (EOMES) is associated with a significantly increased risk to develop chronic lymphocytic leukemia (CLL)." (PMID 33731848, 2021). "Genome-wide association studies identified a single-nucleotide polymorphism (SNP) affecting the transcription factor Eomesodermin (EOMES) associated with a significantly increased risk to develop chronic lymphocytic leukemia (CLL)." (PMID 33731848, 2021).
embryonal carcinoma (1 paper, 2021). A non-seminomatous malignant germ cell tumor characterized by the presence of large germ cells with abundant cytoplasm resembling epithelial cells, geographic necrosis, high mitotic activity, and pseudoglandular and pseudopapillary structures formation. "In this analysis, BIRC5 and EOMES were found to overlap in embryonic stem cells and embryonal carcinoma." (PMID 34685742, 2021).